MIR3671 (microRNA 3671)
Synonyms: hsa-mir-3671
Gene: MicroRNA gene on chromosome 1 (65,057,755 to 65,057,842, reverse strand). Ensembl gene ENSG00000265996.
Homologues: Orthologues: chimpanzee MIR3671 (100% identical).